RORA (RAR related orphan receptor A)
Diseases named in the same sentence as RORA in open-access papers (continued):
Sharing a sentence is not in itself a finding about the gene and the disease.
melanoma (continued). "In our study, we observed expression of RORα in the nuclei (RORαn) of melanoma cells (93.55%), normal uveal melanocytes, (54.84%) and other normal uveal cells (64.52%)." (PMID 31235702, 2019). "RORα and RORγ are expressed in all skin cell types, including epidermal keratinocytes, melanocytes, dermal fibroblasts, and several established lines of malignant melanomas." (PMID 29904382, 2018). "Decreased expression of RORα is positively related with melanoma progression and shorter disease-free and overall survival." (PMID 29904382, 2018). "RORα has been found to be downregulated in keratinocyte-derived skin cancer and is expressed in prostate cancer cells, melanoma cell lines, and BC." (PMID 29904382, 2018). "The relative involvement of the VDR or RORα and γ in the inhibition of melanoma growth by 20(OH)D3 represents a challenging goal for future investigation." (PMID 28039464, 2017). "The comprehensive analysis of mean level of RORα and RORγ revealed that less advanced melanomas (pTis, pT1, and pT2) showed significantly higher RORα and RORγ expression than more advanced melanomas (pT3 and pT4)." (PMID 27542227, 2016). "In keratinocytes of normal skin RORα showed a predominantly nuclear localization, while in cells of melanocytic lesions (nevi, primary melanomas and melanoma metastases) both cytoplasmic and nuclear expression was equally observed." (PMID 27542227, 2016). "In melanocytic tumors, both nuclear and cytoplasmic RORα gradually decreased with the progression of melanocytic lesions and melanomas." (PMID 27542227, 2016). "WB analysis also showed a decrease (relative to Lamin A as control) in RORα or RORγ expression in melanized human melanoma nuclear extracts in comparison to amelanotic cells by 4% and 10%, respectively." (PMID 27542227, 2016). "Cytoplasmic RORα was elevated in keratinocytes of skin surrounding nevi in comparison to keratinocytes of normal skin or keratinocytes of skin surrounding melanomas." (PMID 27542227, 2016). "This was further substantiated by testing of melanoma lines in which induction of melanogenesis by L-tyrosine was accompanied by reduced levels of nuclear RORα and RORγ." (PMID 27542227, 2016). "Since initial studies have shown that the expression of RORα and RORγ in melanomas was aberrant and heterogeneous, further detailed examination is presented in this study." (PMID 27542227, 2016). "Concerning cytoplasmic expression, RORα levels were lower in keratinocytes of normal skin vs cells of melanocytic nevus and primary melanomas; however, a decrease of its expression was seen in primary and metastatic melanomas vs melanocytic nevus." (PMID 27542227, 2016). "The melanomas with high melanin content showed significantly lower levels of nuclear RORα and RORγ than amelanotic and moderately pigmented melanomas." (PMID 27542227, 2016). "We also tested RORα and RORγ expression in cultured melanoma cells using immunofluorescence (IF) and Western Blot (WB) techniques." (PMID 27542227, 2016). "Lack or significant reduction of RORα and RORγ expression in primary melanomas and melanoma metastases would be consistent with this concept." (PMID 27542227, 2016). "Positive correlation between decreased RORα and RORγ expression with progression of melanomas suggests the potential usefulness of RORα and RORγ as new, immunohistochemical marker in melanoma diagnosis, predicting future behavior of the lesion." (PMID 27542227, 2016). "Similar trends for RORα and RORγ expression were also observed for keratinocytes of normal skin vs keratinocytes of skin surrounding nevi and melanomas." (PMID 27542227, 2016). "Specifically, significantly higher nuclear and cytoplasmic RORα and nuclear RORγ levels were found in melanomas with brisk TILs." (PMID 27542227, 2016). "Correspondingly, in the present study the significant reduced RORα and RORγ expression in melanomas correlated to poorer clinical outcome, as determined by overall and disease-free survival time." (PMID 27542227, 2016).
melanoma (continued). "Next, we analyzed the correlation between RORα and RORγ levels in primary melanomas and the presence of tumor-infiltrating lymphocytes (TILs), proliferation activity and histological type." (PMID 27542227, 2016). "The expression of RORα and RORγ was lower in melanomas than in nevi and decreased during melanoma progression, with lowest levels found in primary melanomas at stages III and IV and in melanoma metastases." (PMID 27542227, 2016). "Moreover, hydroxylumisterols, used to suppress the proliferation of human skin cells and melanoma cells, exhibit inverse agonistic effects with respect to RORα and RORγ." (PMID 39518891, 2024). "Furthermore, RORα and RORγ expression correlated to melanoma prognostic markers and was lower in melanomas with higher proliferation rate, presence of ulceration, absent and non-brisk TILs, and nodular histological type." (PMID 38927967, 2024). "In addition, recent studies have indicated that the expression of VDR, RORα, and RORγ in melanomas is related to hypoxia and/or HIF1-α activity, and also affected FoxP3 expression in metastatic melanoma." (PMID 38927967, 2024). "Thus, RORs, particularly RORα and RORγ, are critical for cancer progression, especially with respect to melanoma, highlighting their potential as therapeutic targets aimed at tumor suppression." (PMID 39518891, 2024). "In addition, research highlights that the efficacy of melatonin in inhibiting melanoma growth varies based on the presence of specific receptors, including RORα, and cytosolic proteins present in different human melanoma cell-lines." (PMID 39518891, 2024). "A speculation could be that those polymorphisms interact differently with sex hormones and RORA expression, given the general knowledge that clock genes as well as RORA are down regulated in cancer including melanoma." (PMID 33549124, 2021). "We also tested the correlation between melanin pigmentation and RORα and RORγ expression in primary melanoma tumors, and have found that its nuclear immunoreactivity was inversely correlated with high melanin content (r=−0.2920, P=0.0052 and r=−0.2109, p=0.0399, respectively)." (PMID 27542227, 2016). "The reduced RORα and RORγ levels were also observed in melanized melanomas." (PMID 27542227, 2016). "Melanomas at less advanced stages (Clark levels I and II and Breslow thickness ≤2 mm) showed highest level of both nuclear and cytoplasmic expression of RORα and RORγ." (PMID 27542227, 2016). "We also suggest that targeting RORα and RORγ signaling may represent a promising strategy for melanoma treatment." (PMID 27542227, 2016). "Detailed analysis of melanoma patients stratified according to the level of nuclear RORα expression revealed longer OS in patients with high (median survival 896.1 days) expression of the receptor in comparison to those that lacked nuclear stain (median survival 618.3 days) (χ2 = 7.420, P = 0.0064)." (PMID 27542227, 2016). "Similarly, a significant better prognosis was also observed for melanoma patients with nuclear RORα immunolocalization and with nuclear and cytoplasmic RORγ immunolocalization after adjustment for Breslow thickness." (PMID 27542227, 2016). "Previously, we reported RORα and RORγ expression in cells of human normal skin, including epithelial cells of the epidermis, hair follicle, sebaceous and sweat glands, dermal fibroblasts, immune cells and cultured melanocytes and melanoma lines." (PMID 27542227, 2016). "Similarly, for VDR, RORα and RORγ expression decreased in melanomas with active melanogenesis." (PMID 38927967, 2024). "The expression of receptors of the 20-hydroxylated vitamin D metabolites—retinoic acid-related orphan receptors α (RORα) and retinoic acid-related orphan receptors γ (RORγ) have been observed to negatively correlate with melanoma progression and positively correlate with melanoma prognosis." (PMID 34208589, 2021).
melanoma (continued). "Specifically, nuclear expression of RORα and RORγ was lower in cells of melanomas in comparison to melanocytic nevi and keratinocytes of normal skin and decreased during progression of melanoma, with lowest levels found in primary melanomas at stages III and IV and in melanoma metastases." (PMID 27542227, 2016). "Furthermore, it suggests that RORα and RORγ might constitute a novel druggable target in anti-melanoma management using tumor suppressor gene therapy restoring their normal functions." (PMID 27542227, 2016). "Melanomas at higher advancement (Clark levels III-V and Breslow thickness > 2 mm) presented the lowest levels of both nuclear and cytoplasmic expression of RORα and RORγ." (PMID 38927967, 2024). "In another study, RORγ and RORα expression levels were decreased during melanoma progression, with the lowest expression levels in stages III and IV primary melanomas and in melanoma." (PMID 29904382, 2018). "Although we detected a strong nuclear expression of both RORα and RORγ in human normal skin, ROR expression showed a very heterogeneous pattern in four invasive melanoma samples." (PMID 27542227, 2016). "The WB confirmed expression of RORα and RORγ in both nuclear and cytoplasmic fractions of human SKMEL and hamster AbC1 melanomas, as well as control HEPA cells overexpressing RORs." (PMID 27542227, 2016). "The detailed analysis of RORα and RORγ in primary melanomas stratified according to Clark and Breslow levels revealed significant negative correlation between expression of RORα and RORγ and progression of melanoma." (PMID 27542227, 2016). "To study the potential role of RORs in melanoma progression, we analysed RORα and RORγ expression in nevi and primary melanomas and non-lesional skin and metastases in relation to melanoma clinico-pathomorphological features." (PMID 27542227, 2016). "Importantly, there was a correlation between the expression of RORα and RORγ in primary melanomas and OS and DFS in cohort of melanoma patients included into this study." (PMID 27542227, 2016). "Similarly, more aggressive nodular type melanomas (NM) showed substantial decrease of RORα and RORγ expression (both nuclear and cytoplasmic) in comparison to superficial spreading (SSM) melanomas." (PMID 27542227, 2016). "Additionally, in a melanoma-based study, HDAC3 acted as a competitive receptor for DDX3X, forming an inhibitory complex with the retinoic acid receptor-related orphan receptor-alpha (RORA)." (PMID 40006729, 2025). "RORα and γ, alternative receptors for vitamin D-hydroxyderivatives, are expressed at lower levels in melanomas than in nevi and their expression decreases during melanoma progression, with lowest expression found in stage III and IV melanomas and in metastases." (PMID 34692525, 2021). "Moreover, these relationships were more pronounced for RORα expression and vertical growth phase of melanomas (data not shown)." (PMID 27542227, 2016). "We also analyzed in detail relative expression of RORs in relation to the ability to develop metastases and found that primary melanomas that metastasized showed reduced nuclear and cytoplasmic expression of RORα and RORγ in comparison to non-metastasizing melanomas." (PMID 27542227, 2016). "RORα and RORγ antigens were detected in both cytoplasmic and nuclear compartments of melanoma cells, and in positive controls consisting of HEPA cells overexpressing RORα or RORγ, while being absent in negative controls." (PMID 27542227, 2016).
cerebellar ataxia (18 papers, 2011 to 2025). A neurological syndrome characterized by clumsy and uncoordinated movement of the limbs, trunk, and cranial muscles. "Rorα spontaneous (staggered mouse) or engineered mutations cause ataxia and cerebellar neurodegeneration, with synaptic arrangement and immature morphology of cerebellar neurons (Purkinje)." (PMID 40631402, 2025). "RORα silencing caused the degradation of Purkinje cells and the development of the cerebellar ataxia phenotype, confirming the key role of RORα in the etiology of SCA1 and SCA3." (PMID 35625877, 2022). "RORα knockout mice (RORα-KO; staggerer phenotype) develop a progressive PC and GrC loss (about 80%;) combined with severe ataxia." (PMID 35409253, 2022). "Genetically modified mice, in which RORα is disrupted, and RORα-deficient staggerer (RORαsg/sg) mice display severe cerebellar ataxia due to cerebellar neurodegeneration." (PMID 26878025, 2015). "AAV-mediated knock down of RORα also lead to degeneration of Purkinje cell layer alignment, dendritic atrophy and ataxia, suggesting that loss of RORα function may be involved in SCA disease phenotypes." (PMID 32765211, 2020). "Thus, RORA gene mutations are linked to both ataxia and epilepsy in humans." (PMID 32714261, 2020). "Of interest, childhood-onset genes with the highest cerebellar molecular layer interneuron cell-type expression were associated with ataxia syndromes manifesting partially or fully with seizures (e.g. KCNA1 and RORA)." (PMID 36624280, 2023). "In a recent study, the rAAV was used in a mouse model to investigate the contribution of RORα downregulation on cerebellar motor function and the ataxia phenotype." (PMID 35625877, 2022). "One of the first animal models of human ataxia, the staggerer mutant mouse, was later found to lack functional RORα." (PMID 32765211, 2020). "Aware that RORA has been shown to be an important modifier of the cerebellar ataxia in SCA1 mouse models, we extended the analysis to the cerebellum of SCA2 mouse models." (PMID 26868665, 2017). "The RORA gene is known to be associated with intellectual disability with or without epilepsy or cerebellar ataxia, in autosomal dominant inheritance (OMIM #618060)." (PMID 40033291, 2025). "In addition to these key functions during development, RORα is required throughout life to maintain PC dendrites and survival, for example ITPR1 deficiency causes the adult-onset spinocerebellar ataxia 15 with its associated PC loss." (PMID 37066074, 2023). "RORα was first discovered to be involved in the onset of cerebellar ataxia." (PMID 34584074, 2021). "These EIIARORα KO mice, which expressed significantly reduced RORα expression relative to WT mice but did not display mobility/ataxia issues typically associated with loss of RORα function, were protected against diet- and age-induced metabolic syndrome." (PMID 28744254, 2017). "In conclusion, we developed a new RORα deficiency mouse model that recapitulates the observations performed in the Staggerer mice but without the problematic effects of ataxia." (PMID 28744254, 2017). "The RORα null mice display an identical phenotype recapitulating the severe ataxia." (PMID 28744254, 2017). "SQSTM1 variants are associated to frontotemporal dementia and/or amyotrophic lateral sclerosis-3 (FTDALS3, MIM #616437) while RORA alterations are associated to intellectual developmental disorder with or without epilepsy or cerebellar ataxia (IDDECA, MIM #618060)." (PMID 40208338, 2025). "RORα defects are connected in humans with intellectual development disorder with or without epilepsy, or cerebellar ataxia, (OMIM #600825)." (PMID 40631402, 2025). "In this study, we describe a new mouse model of deletion of RORα that does not display ataxia providing an improved model for assessing RORα-dependent metabolism where “normal” feeding behavior and locomotion are retained." (PMID 28744254, 2017).
cerebellar ataxia (continued). "The residual RORα expression in the brain may explain why the EIIaRORα KO mice do not display ataxia." (PMID 28744254, 2017).
diabetes (17 papers, 2011 to 2025). "By employing mouse line having RORα deletion, researchers exhibited that deficiency of RORα deteriorated diastolic function and augmented diabetes-induced cardiac remodeling." (PMID 39114353, 2024). "We conclude that prenatal RORA deficiency partly mimics maternal diabetes-mediated ALB, while it has little effect on anxiety-like behavior in offspring." (PMID 35027651, 2022). "We evaluated the potential effect of prenatal RORA deficiency on maternal diabetes-mediated animal behaviors." (PMID 35027651, 2022). "We evaluated the potential effect of RORA deficiency on maternal diabetes-mediated gastrointestinal dysfunction." (PMID 35164690, 2022). "More interestingly, RORA deficiency in the amygdala completely mimicked maternal diabetes-mediated reduced synaptophysin expression and spine density in amygdala neurons." (PMID 35027651, 2022). "Further experiments using the RORA knockout (RORA−/−) mouse model showed that intestine-specific RORA deficiency mimicked or worsened maternal diabetes-mediated oxidative stress and inflammation in IEC as well as GI symptoms." (PMID 35164690, 2022). "In general, our results indicate that intestine-specific RORA deficiency mimics or worsens maternal diabetes-mediated gastrointestinal dysfunction, including cytokine release, increased intestinal permeability and changes of the gut microbial composition." (PMID 35164690, 2022). "Our results showed that RORA deficiency had little effect on maternal diabetes-mediated anxiety-like behaviors, as measured in the MBT and elevated plus maze (EPM) tests." (PMID 35027651, 2022). "We then evaluated the potential effect of prenatal RORA deficiency on maternal diabetes-mediated gene expression and oxidative stress." (PMID 35027651, 2022). "RORA agonist SR1078 partly reversed this effect, and intestine-specific RORA deficiency mimics or worsens maternal diabetes-mediated GI symptoms." (PMID 35164690, 2022). "RORα variants are linked with an increased possibility of developing diabetes, while PER3 and RORα polymorphisms increase the risk of MetS in the Taiwanese population." (PMID 35053018, 2021). "The in vivo mouse study shows that prenatal RORA deficiency in neuron-specific RORA null mice mimics maternal diabetes-mediated ALB; postnatal RORA expression in the amygdala ameliorates, while postnatal RORA knockdown mimics, maternal diabetes-mediated ALB in offspring." (PMID 35027651, 2022). "Furthermore, IEC-specific RORA deficiency either mimics or worsens maternal diabetes-mediated GI symptoms." (PMID 35164690, 2022). "We conclude that prenatal RORA deficiency mimics maternal diabetes-mediated oxidative stress." (PMID 35027651, 2022). "RORα regulates myriad metabolic pathways and based on the phenotype of the staggerer mice as well as the RORα null mice, RORα is a potential target to treat diseases such as atherosclerosis, diabetes, and osteoporosis as well as disorders associated with disruption of the circadian rhythm." (PMID 22485150, 2012). "As a natural ligand of RORα, CS holds significant potential in influencing the pathogenesis and progression of diabetes." (PMID 40427539, 2025). "RORα plays a role in controlling blood glucose homeostasis and the development of diabetes by modulating gluconeogenesis and is also closely associated with lipogenesis, insulin production, and insulin sensitivity." (PMID 40427539, 2025). "Studies have also demonstrated the mechanistic roles of RORα in diabetic cardiac tissues and epithelial cells of the proximal tubules during renal I/R injury diabetes by demonstrating that RORα levels are reduced in these pathologies." (PMID 39518891, 2024). "Dams were treated by control (CTL/VEH), diabetes (STZ/VEH), diabetes plus SOD mimetic MnTBAP (STZ/MnTBAP), or diabetes plus RORA agonist SR1078 (STZ/SR1078) during pregnancy." (PMID 35164690, 2022).